SENP3-EIF4A1 (SENP3-EIF4A1 readthrough (NMD candidate))
Gene: Protein-coding gene on chromosome 17 (7,563,287 to 7,578,715, forward strand). Ensembl gene ENSG00000277957.
Genetic constraint (gnomAD): Missense variants: 457 observed, 643.24 expected, observed/expected ratio (o/e) 0.71, 90% interval 0.66 to 0.77. Synonymous variants: 246 observed, 242.68 expected, observed/expected ratio (o/e) 1.01, 90% interval 0.91 to 1.13.